PLD1 (phospholipase D1)
Description:
Function as phospholipase selective for phosphatidylcholine. Implicated as a critical step in numerous cellular pathways, including signal transduction, membrane trafficking, and the regulation of mitosis. May be involved in the regulation of perinuclear intravesicular membrane traffic (By similarity).
Synonyms: CVDD; CVDP1
Tractability: Small molecule: a high-quality ligand is known; it belongs to a druggable protein family. Antibody: its Gene Ontology location is reachable by antibodies, with high confidence; the Human Protein Atlas places it where antibodies can reach. PROTAC: ubiquitination databases record sites on it; its protein half-life has been measured; a small molecule that binds it is known.
Target class: Enzyme; Hydrolase
Chemical probes: ML272, VU0359595 (high quality), VU69 (high quality)
Gene: Protein-coding gene on chromosome 3 (171,600,404 to 171,810,950, reverse strand). Ensembl gene ENSG00000075651.
Subcellular location: Cytoplasm, perinuclear region; Endoplasmic reticulum membrane; Golgi apparatus membrane; Late endosome membrane
Subcellular location (Human Protein Atlas): Plasma membrane; Golgi apparatus; Vesicles
Pathways (Reactome):
Signal Transduction: CDC42 GTPase cycle; RAC1 GTPase cycle; RHOA GTPase cycle; RHOG GTPase cycle
Immune System: Neutrophil degranulation; Role of phospholipids in phagocytosis
Metabolism: Synthesis of PA; Synthesis of PG
Gene Ontology:
Molecular function: phospholipase D activity; protein binding; catalytic activity; phosphatidylinositol binding
Biological process: cellular response to nutrient; positive regulation of translation; regulation of synaptic vesicle cycle; chemotaxis; phosphatidic acid biosynthetic process; Ras protein signal transduction; regulation of vesicle-mediated transport; small GTPase-mediated signal transduction; intracellular signal transduction
Cellular component: apical plasma membrane; cholinergic synapse; endocytic vesicle; endosome; Golgi apparatus; lysosomal membrane; lysosome; membrane; cytoplasmic vesicle; endoplasmic reticulum membrane; Golgi membrane; late endosome membrane; plasma membrane; specific granule membrane; tertiary granule membrane; cytoplasm; endomembrane system; organelle subcompartment; perinuclear region of cytoplasm
Genetic constraint (gnomAD): Loss-of-function variants: 31 observed, 50.93 expected, observed/expected ratio (o/e) 0.61, 90% interval 0.46 to 0.82. The upper end of that interval is the gene's LOEUF score, 0.82, which puts it in group 3 of 6, group 1 being the genes least tolerant of losing a copy. Missense variants: 611 observed, 652.74 expected, observed/expected ratio (o/e) 0.94, 90% interval 0.88 to 1. Synonymous variants: 216 observed, 231.21 expected, observed/expected ratio (o/e) 0.93, 90% interval 0.83 to 1.05.
Gene-disease validity (ClinGen):
ClinGen rates the evidence that PLD1 causes each of these diseases.
PLD1-related congenital heart disease (autosomal recessive): Definitive. Any congenital heart disease in which the cause of the disease is a mutation in the PLD1 gene.
Homologues: Orthologues: chimpanzee PLD1 (99% identical), macaque PLD1 (98% identical), pig PLD1 (93% identical), dog PLD1 (93% identical), mouse Pld1 (91% identical), rat Pld1 (91% identical), guinea pig PLD1 (91% identical), rabbit PLD1 (89% identical), tropical clawed frog pld1 (75% identical), zebrafish pld1a (66% identical), zebrafish pld1b (66% identical), Caenorhabditis elegans pld-1 (43% identical), and 1 more. Paralogues in human: PLD2 (49% identical).
Diseases named in the same sentence as PLD1 in open-access papers:
PLD1 is named in the same sentence as 115 diseases in open-access papers, as found by Europe PMC text mining. Sharing a sentence is not in itself a finding about the gene and the disease. The quoted sentences say what the papers report.
breast carcinoma (13 papers, 2007 to 2022). "Evidence shows that breast cancer cells treated with doxorubicin increased PCho/GPC ratio caused by a downregulation of the enzymes PLD1, GDPD6, and ChoKα." (PMID 35250970, 2022). "Phospholipase D1 has been implicated in breast cancer tumorigenesis and has been proposed to play a role in oestrogen-independent growth." (PMID 17726467, 2007). "Kang and colleagues concluded from their findings that the invasion of breast cancer cells was related to both higher PLD1 expression levels and increased PLD1 activity." (PMID 33832505, 2021). "The present study demonstrates that PLD2 is upregulated by HDAC inhibitor and PLD1 inhibition increases HDAC inhibitor-induced apoptosis of breast cancer cells." (PMID 32998768, 2020). "PLD1 is the medium-membrane protein that is overexpressed in various cancers, such as lung cancer, breast cancer, and kidney cancer." (PMID 32697311, 2020). "Meanwhile, some other reports suggested that PLD1 inhibition in combine with ionizing radiation was effective in inducing DNA damage, and breast cancer cell apoptosis subsequently." (PMID 28915652, 2017). "Genetically enforced overexpression of PLD1 or PLD2 in a human breast cancer xenograft model led to primary tumor initiation and increased metastasis." (PMID 28083512, 2016). "PLD inhibitors clearly inhibit the invasion of breast cancer cells in culture and, similarly, inhibition of PLD1 and PLD2 by triptolide decreases cell proliferation in MDA-MD-231 cells." (PMID 24103483, 2014). "The results from Chen and colleagues are intriguing and in this study, we have used clinical tissues to evaluate the expression of PLD1 with phospho-Akt and phospho-mTOR in breast carcinomas to help facilitate patient selection for mTOR-targeted therapies." (PMID 17726467, 2007). "Our findings that PLD1 is overexpressed in TMX2-28 breast cancer cells and in a subset of breast tumours are consistent with the published data." (PMID 17726467, 2007). "Importantly, silencing of the metabolic enzymes PLD1 and ChoKα sensitized breast cancer cells to doxorubicin and specific GDPD6 silencing counteracted doxorubicin migration induction." (PMID 35250970, 2022). "PLD1 exhibits a higher expression level in colorectal tumours, bladder cancer and breast cancer." (PMID 35775110, 2022). "Interestingly, while PLD2 was found to impact exosome secretion by governing ILV biogenesis in a different breast carcinoma cell line, our data rather suggest that PLD1 controls exosome biogenesis in 4T1 cells." (PMID 33404012, 2021). "It has also been reported that platelet derived growth factor (PDGF) increased PLD1, which could then facilitate the invasion of breast cancer cells." (PMID 29088790, 2017). "Moreover, it was recently shown that by silencing ChKα in breast cancer cells, PtdCho–PLD1 was in turn upregulated and vice versa." (PMID 28083512, 2016). "Breast cancer cells (SK-BR3) had increased invasion due to a similar PLD1/MMP model." (PMID 24103483, 2014). "We next examined PLD1 expression in human breast carcinomas." (PMID 17726467, 2007). "Patients with tumours expressing activated PLD1/mTOR signalling may be sensitive to rapamycin-based therapies; however, it has been shown that high levels of PLD1 confers rapamycin resistance in MDA-MB-231 breast cancer cells in vitro." (PMID 17726467, 2007). "Therefore, it is plausible that those patients with tumours positive for ER and PLD1 will respond to combined anti-hormone and rapamycin-based therapies; that combination has been successful in inhibiting the proliferation of breast cancer cell lines." (PMID 17726467, 2007). "To determine whether PLD1 gene expression correlates with either the basal or luminal CKs and/or ER status in breast tumour tissue, we isolated RNA from 30 frozen human–breast carcinomas and evaluated gene expression by real-time RT–PCR." (PMID 17726467, 2007). "The levels of PLD1 mRNA were evaluated in the 30 frozen human–breast carcinomas." (PMID 17726467, 2007).
breast carcinoma (continued). "For example, in aggressive ER− breast cancers, GDPD5, PLD1, and ChKα, were simultaneously highly expressed, leading to elevated PC and tCho levels." (PMID 28083512, 2016). "Both PLD1 and PLD2 selective inhibitors were found to enhance the radiosensitivity of breast cancer cells." (PMID 28083512, 2016). "To evaluate further the relationship of PLD1 with phospho-Akt, we used TMA and IHC technology to examine 42 breast carcinomas." (PMID 17726467, 2007). "However, Diaz-Aragon and colleagues concluded from their data that both PLD1 and PLD2 were involved in the linoleic acid-induced migration and invasion as well as sphere formation of MDA-MB-231 human breast cancer cells." (PMID 33832505, 2021). "Hence, PLD1 activity seems necessary for EGF-induced calcium release in MDA-NEO and MDA-HER2 human breast cancer cells." (PMID 33832505, 2021). "GDPD5, as well as PLD1 and ChKα, were highly expressed in estrogen receptor negative (ER−) breast cancers, which also displayed higher PC, tCho, and lower GPC in comparison with ER+ cases." (PMID 28083512, 2016). "In a subset of breast cancer cells that are negative for phospho Akt, the PLD1/mTOR pathway is active, suggesting that PLD1 is a major survival signal in this scheme." (PMID 24103483, 2014). "The authors reported that MDA-MB-231 cells have high-PLD1 activity, which is responsible for promoting mTOR-dependent survival signals in these breast cancer cells that do not express active PI3K/Akt survival signals." (PMID 17726467, 2007). "In this study, we report that PLD1 and phospho-mTOR are coexpressed in a subset of phospho-Akt-negative breast carcinomas." (PMID 17726467, 2007). "In this study, we are the first to demonstrate that the PLD1/mTOR pathway is active in a subset of clinical breast carcinomas that are negative for phospho-Akt." (PMID 17726467, 2007). "When treated with isoform-specific PLD inhibitors, the viability of MDA-MB-231 breast cancer cells grown in the regular culture medium that contained high glucose (25 mM) was not significantly altered by either the PLD1 inhibitor (PLD1i) or PLD2 inhibitor (PLD2i)." (PMID 27809301, 2016).
Obesity (9 papers, 2013 to 2022). Accumulation of substantial excess body fat. "Another genetic trait, which has been shown to be involved in the development of obesity, is represented by the human phospholipase D1-encoding gene (pld1)." (PMID 28638490, 2017). "For example, we identified an association between a taxon known to affect obesity (genus Akkermansia) and a variant near PLD1, a gene previously associated with body mass index." (PMID 26528553, 2015). "The gene product of pld1 was shown to provoke glycerol phospholipid hydrolysis with the concomitant production of phosphatidic acid, which is an intracellular messenger implicated in several cellular processes, including obesity." (PMID 28638490, 2017). "Insulin deficiency or insulin resistance also contributes to obesity by lowering the levels of phospholipase enzyme while the excess phospholipase D1 and D2 expressed in rodents suppress obesity." (PMID 35388304, 2022). "Mice deficient in PLD1 and PLD2 consumed more food and developed obesity, as well as resistance indicating PLD protective role against obesity and its associated metabolic disorders." (PMID 32899471, 2020). "Thus, the existence of correlations between a polymorphism of PLD1 and this bacterial taxon may represent an example of how host-associated genotype that is responsible for a specific gut microbiota profile, ultimately influencing the development of obesity." (PMID 28638490, 2017). "Studies of adipose-tissue-specific PLD1 knockout mice are needed to confirm our observations in vivo, and to assess any adipose tissue-specific contribution to obesity." (PMID 27872488, 2016). "Although this finding supports that PLD1 is a negative regulator of adipogenesis, it is most unlikely that PLD deficiency elicits obesity simply due to a defect in adipose tissue." (PMID 27872488, 2016). "They observed obvious obesity in 20-week old Pld1−/− mice, followed by increase in free fatty acid (FFA) levels and glucose levels in the blood of Pld1−/− mice." (PMID 27976696, 2016). "PLD1 knockout mice consume more food due to defects in the hypothalamus, which results in obesity." (PMID 33014279, 2020). "Furthermore, these new molecular discoveries may prompt the development of PLD1-specific activation methods as a therapeutic strategy for treating obesity." (PMID 27872488, 2016). "The purpose of this study was to examine the role of phospholipase D1 (PLD1) in leptin-induced expression of the proinflammatory cytokine, tumor necrosis factor (TNF)-α, and to suggest a molecular link between obesity and respiratory tract inflammation." (PMID 25047119, 2014). "Our results also suggest that this strategy is effective in a mouse model of obesity-induced insulin resistance, and support further efforts aimed at generating novel molecules that interfere with PED/PEA-15 and/or PLD1 functions mimicking D4 peptide action." (PMID 23585839, 2013).
colorectal cancer (8 papers, 2010 to 2023). A primary or metastatic malignant neoplasm that affects the colon or rectum. "In trials, the researchers observed downregulation of PLD1’s associated signaling pathway, and reductions in the ability of colorectal cancer cells to migrate, invade and replicate." (PMID 36131027, 2022). "Several studies have reported expression of PLD1 in various human cancers, such as breast, kidney, gastric, thyroid, and colorectal cancers." (PMID 37381714, 2023). "The high expression of PLD1 in tumour tissues is related to a poor prognosis in patients with colorectal cancer and bladder cancer." (PMID 35775110, 2022). "Collectively, in this study, PLD1 was identified as a critical regulator of the tumor microenvironment in colorectal cancer, suggesting the potential of PLD1 inhibitors for cancer immunotherapy based on ICD and immune activation." (PMID 36131027, 2022). "Our previous miRNA array analysis of PLD1 inhibitor‐treated colorectal cancer (CRC) cells identified miRs induced by PLD1 inhibitor." (PMID 32725633, 2020). "Wnt3a can enhance the expression and activity of phospholipase D1 (PLD1; a cell survival mediator) in many types of cancer cells and enhance the expression of PLDs at a transcriptional level, as shown in colorectal cancer HCT116 cells." (PMID 26369691, 2015). "Elevated expression of PLD1 and PLD2 has been reported in colorectal cancer tissues; in particular, PLD2 expression level and its association with clinicopathological features have recently been investigated in colorectal carcinoma." (PMID 20711340, 2010). "Elevated expression of PLD1 and PLD2 has been reported in colorectal cancer tissues." (PMID 20711340, 2010). "To further confirm whether endogenous SIRT1 and PLD isozymes can form a natural complex in colorectal cancer cells (HT119 and HT29 cells) and A549 lung adenocarcinoma cells, which express both endogenous PLD1 and PLD2, we performed coimmunoprecipitation assays." (PMID 34471223, 2021).
Sepsis (8 papers, 2010 to 2023). Sepsis is defined as life-threatening organ dysfunction caused by a dysregulated host response to infection. "In this study we have shown that PLD1 deficiency in mice results in a significant survival advantage after LPS-induced sepsis." (PMID 29968773, 2018). "PLD1 deficient platelets contribute to preserved outcome after LPS-induced sepsis because platelets exhibit an integrin activation defect suggesting reduced platelet activation in PLD1 deficient mice." (PMID 29968773, 2018). "Therefore, we wanted to know if PLD1 deficient platelets contribute to improved survival of mice after LPS-induced sepsis." (PMID 29968773, 2018). "Deficiency of PLD1 protects mice from organ damage, inflammation, massive thrombin generation and cell apoptosis resulting in enhanced survival of mice after LPS induced sepsis." (PMID 29968773, 2018). "Interestingly, PLD1 mediates TNF-α regulation via MEK1 and ERK phosphorylation leading to reduced Egr1 expression after LPS-induced sepsis in PLD1 deficient mice." (PMID 30555342, 2018). "It is thus plausible that the TLR4/MyD88/PLD1 axis mediates increases in PA pools that serve as substrates for lipin-1 during the events of macrophage proinflamatory activation and sepsis development described in this study." (PMID 34757442, 2021). "Here, we evaluated the effects of a phospholipase D1 (PLD1)-selective inhibitor (VU0155069) against sepsis and inflammasome activation." (PMID 31586128, 2019). "Our data revealed that PLD1 is a key regulator of TNF-α expression upon sepsis because PLD1 plays a major role in the MEK-ERK1/2 mitogen-activated protein kinase (MAPK) pathway upon LPS induction of TNF-α gene expression." (PMID 29968773, 2018). "Phospholipase D1 is a regulator of tumor necrosis factor-α expression and release upon LPS-induced sepsis and following myocardial infarction (MI)." (PMID 30555342, 2018). "In this study we show that PLD1 is crucial for the TNF-α induced inflammatory response after LPS-induced sepsis in mice thereby regulating TNF-α expression and release, cell survival and thrombin generation and fibrin formation in septic mice." (PMID 29968773, 2018). "We next investigated the potential of PLD1 to modulate cell survival and apoptosis after LPS induced sepsis." (PMID 29968773, 2018). "Based on these findings PLD1 is a promising new target to be further developed as a drug candidate for therapy of sepsis." (PMID 29968773, 2018). "We investigated the effects of a PLD1 inhibitor (VU0155069) against a mouse model of sepsis." (PMID 31586128, 2019). "The present study has identified PLD1 as a regulator of innate immunity that may be a new target to modulate sepsis." (PMID 29968773, 2018). "after LPS-induced sepsis in Pld1−/− mice compared to Pld1+/+ controls." (PMID 29968773, 2018). "Indeed, our results suggest PLD1 as a novel target for treating inflammatory diseases, where TNFα play key roles: these include diseases ranging from sepsis to respiratory and autoimmune diseases; all diseases with considerable unmet medical need." (PMID 20463923, 2010). "In this study we analyzed the impact of PLD1 in the regulation of TNF-α, inflammation and organ damage in experimental sepsis." (PMID 29968773, 2018). "PLD1 is crucial for TNF-α mediated inflammation after MI and LPS-induced sepsis in mice." (PMID 30555342, 2018). "Here we identified PLD1 as regulator of TNF-α expression and release upon experimental sepsis." (PMID 29968773, 2018). "PlD1 alone did not confer protection against sepsis; all mice died within four days of infection." (PMID 38096222, 2023). "However, the function and regulation of PLD1 in sepsis has not been explored to date." (PMID 29968773, 2018).